PVT1 (Pvt1 oncogene)
Diseases named in the same sentence as PVT1 in open-access papers (continued):
Sharing a sentence is not in itself a finding about the gene and the disease.
glioma (continued). "Moreover, to explore the relationship between PVT1 expression and glioma patients’ prognosis, we attempted to assess the correlation between PVT1 levels and clinical outcomes." (PMID 29046366, 2017). "In addition, gliomas with chemotherapy tended to have a higher PVT1 expression." (PMID 37202742, 2023). "However, the clinical significance and underlying mechanism of PVT1 was not be fully explored in glioma." (PMID 37202742, 2023). "Also, the expression of PVT1 increased with increasing grades of glioma." (PMID 37891744, 2023). "Taken together, the results implied that PVT1 might play a key role in glioma chemoresistance." (PMID 37202742, 2023). "PVT1 may become a potential biomarker for the diagnosis and treatment in glioma." (PMID 37202742, 2023). "Thus, deeply investigating the molecular mechanism and functional diversity of PVT1 in glioma may help to get a potential therapeutic target in glioma." (PMID 37202742, 2023). "Furthermore, PVT1 negatively regulated miR−200a, which has a critical role in glioma development." (PMID 34322395, 2021). "In conclusion, the identification of PVT1 as an important prognostic factor for glioma patients induced our interests to explore its functional roles, and finally we found that PVT1 could regulate glioma cell proliferation and invasion both in vitro and in vivo." (PMID 29046366, 2017). "Kaplan-Meier survival curve and Cox regression analyses showed that glioma patients with high PVT1 expression or low HAR1A expression had poor survival outcome, aberrantly expressed PVT1 and HAR1A could be the independent prognosis biomarkers for glioma patients." (PMID 29108264, 2017). "Importantly, we first found that PVT1 may regulate glioma proliferation and invasion via target EZH2." (PMID 29046366, 2017). "Moreover, we inferred that PVT1 was an upstream regulatory gene of EZH2, and PVT1 may modulate glioma cell proliferation and invasion via EZH2." (PMID 29046366, 2017). "PVT1 gene amplification in GBM and its expression correlate with molecular grading, serving as an indicator of poor prognosis in gliomas." (PMID 38287522, 2024). "In glioma, recent research demonstrates that the long non-coding RNA PVT1 oncogene enhances stemness and resistance to temozolomide (TMZ) in glioma through the miR-365/ELF4/SRY-Box Transcription Factor 2 (SOX2) pathway." (PMID 39132148, 2024). "PVT1 and miR-365 expressions are negatively correlated, and the overexpression of miR-365 suppresses TMZ resistance in glioma cells." (PMID 36819921, 2023). "In this study, we collected the transcriptome and genomic data of 1210 glioma samples from CGGA, TCGA and GSE16011 cohorts to analyze the molecular and clinical characteristics of PVT1 comprehensively." (PMID 37202742, 2023). "This review compiles several differentially expressed lncRNAs in IDH-mutant and IDH-wildtype gliomas, and it has been shown that lncRNAs SBF2-AS1, PVT1, MALAT1, and H19 significantly contribute to the induction of TMZ resistance." (PMID 36819921, 2023). "We found MGMT promotor unmethylated glioma (p = 0.0072), recurrent glioma (p = 0.041), or with TMZ chemotherapy (p = 0.037) patients had higher level of PVT1 expression." (PMID 37202742, 2023). "In glioma, increased TMZ resistance, conferred by the upregulations of risky lncRNAs such as H19, MALAT1, PVT1, and SBF2-AS1, is likely to play a key role in the therapeutic efficacy of surgical resection plus drug treatment." (PMID 36819921, 2023). "In TCGA dataset, we observed that PVT1 was the highest expressed in the GBM (p < 0.0001) (WHO grade IV) compared with WHO grade II and grade III glioma." (PMID 37202742, 2023). "It has also been reported that long non‐coding RNA PVT1 induces up‐regulation of SOX2 expression through the miR‐365/ELF4 axis, thereby promoting the maintenance of stemness and TMZ resistance in glioma cells." (PMID 36184801, 2022).
glioma (continued). "Knockdown of PVT1 and overexpression of miR‐365 has been found to inhibit stemness and TMZ resistance of glioma cells." (PMID 36184801, 2022). "In glioma, UPF1 was reported to be downregulated in U87 and LN229 cell lines after acting with LncRNA PVT1." (PMID 35871061, 2022). "LncRNA PVT1 upregulates miR-128-3p-regulated downstream signal transduction molecules GREM1 and BMP and promotes malignancy and glioma development." (PMID 36793341, 2022). "LncRNA PVT1 promotes the expression of BMP2 and BMP4 by regulating GREM1 expression and promoting glioma progression." (PMID 35113786, 2022). "PVT1 also upregulated miR-190a-5p and miR-488-3p, resulting in inhibited expression of myocyte enhancer factor 2C (MEF2C), an oncogenic factor in glioma." (PMID 34322395, 2021). "A nine-EMT-related lncRNAs (HAR1A, LINC00641, LINC00900, MIR210HG, MIR22HG, PVT1, SLC25A21-AS1, SNAI3-AS1, and SNHG18) signature was identified in patients with glioma." (PMID 34288803, 2021). "For example, the abnormal expression of PVT1 affects the expression of NANOG and thus makes difference in the development of glioma." (PMID 35127729, 2021). "PVT1 overexpression increased the expression of ATG7 and Beclin1 by targetting miR-186, which induced protective autophagy, thus promoting glioma vascular endothelial cell proliferation, migration, and angiogenesis." (PMID 30266744, 2018). "The expression levels of PVT1 and EZH2 in human glioma tissues and cell lines were measured using quantitative RT-PCR (qRT-PCR)." (PMID 29046366, 2017). "Recent study found that PVT1 contributed to tumorigenesis of thyroid cancer through recruiting enhancer of zeste homolog 2 (EZH2), and promoting glioma vascular endothelial cell proliferation, migration, and angiogenesis by targetting miR-186." (PMID 29046366, 2017). "However, the functional role and molecular mechanism of PVT1 in glioma remain unclear." (PMID 29046366, 2017). "Therefore, we infer that PVT1 may modulate glioma cell proliferation and invasion via EZH2." (PMID 29046366, 2017). "We found that the expression levels of both PVT1 and EZH2 were up-regulated in human glioma tissues and cell lines, and positively correlated with glioma malignancy." (PMID 29046366, 2017). "Further analysis of TCGA and GEO data revealed that the expressions of PVT1 and CYTOR were up-regulated, while HAR1A and MIAT expressions were down-regulated in gliomas." (PMID 29108264, 2017). "In the present study, first, we had measured the aberrant PVT1 and EZH2 expression in clinical glioma tissue samples and glioma cell lines." (PMID 29046366, 2017). "The expressions of PVT1 and EZH2 in normal brain tissues, glioma tumor tissues, and glioma cell lines were analyzed by qRT-PCR." (PMID 29046366, 2017). "Moreover, the down-regulation of PVT1 and up-regulation of HAR1A improved the survival of glioma patients that received chemotherapy and radiotherapy." (PMID 36819921, 2023). "PVT1 competitively binds to miR-365 and positively regulates the expression of E74 like ETS transcription factor 4 (ELF4), which contributes to the induction of glioma stemness and TMZ resistance." (PMID 36819921, 2023). "The overexpression of PVT1 and downregulation of miR-128-3p provoke the upregulation of gremlin 1 (GREM1), promoting cell proliferation, invasion and migration whilst inhibiting apoptosis in glioma cells." (PMID 34202078, 2021). "Among the nine EMT-related lncRNAs identified in this study, LINC00900, MIR210HG, MIR22HG, PVT1, and SNHG18 were positively correlated with glioma malignancy, whereas HAR1A, LINC00641, SLC25A21-AS1, and SNAI3-AS1 were negatively correlated with glioma malignancy." (PMID 34288803, 2021). "In vitro and in vivo studies verified that PVT1 overexpression could up-regulate EZH2 mRNA and protein levels in glioma." (PMID 32117705, 2020).
glioma (continued). "Within glioma samples of TCGA along with LGG subtypes, the overall survival of low PVT1 expression group was significantly better than that of high expression group in glioma patients who received chemotherapy (P <0.0001 and P =0.0004) or radiotherapy (P <0.0001 and P =0.0005)." (PMID 29108264, 2017). "Taken together, these results suggested that both PVT1 and EZH2 expression levels were positively correlated with glioma malignancy, and may play an important role in glioma progression." (PMID 29046366, 2017). "Subsequent multivariate analysis results revealed that high PVT1 expression (HR: 2.539, P <0.001) and low HAR1A expression (HR: 1/0.625=1.6, P = 0.021) were the independent prognosis factors for survival of glioma patients, in addition to increased age, high KPS and grade." (PMID 29108264, 2017). "Interestingly, we found that PVT1 was not only played an important role in tumor progression, but was also tightly related to the sensitivity of TMZ chemotherapy via JAK/STAT signaling in glioma." (PMID 37202742, 2023). "Glioma patients with high PVT1 expression and low HAR1A expression had poor survival outcome, up-regulated PVT1 and down-regulated HAR1A could be the independent prognosis factors for glioma patients." (PMID 29108264, 2017). "However, the expression levels of Neat1, Mir142hg, Pvt1, Mir17hg, SNHG12 and Meg3 showed opposite trends, which may correlate with the distinct inflammatory profiles and immunophenotypes of the different glioma models analyzed." (PMID 40527978, 2025). "Furthermore, survival curve and Cox regression analyses showed that glioma patients with high PVT1 expression or low HAR1A expression had poor survival outcome, aberrantly expressed PVT1 and HAR1A could be the independent prognosis biomarkers for diffuse glioma patients." (PMID 29108264, 2017). "PVT1 and CYTOR expressions were remarkably increased in glioma samples compared with non-tumor controls (both P <0.001)." (PMID 29108264, 2017).
hepatocellular carcinoma (63 papers, 2012 to 2025). A malignant tumor that arises from hepatocytes. "A pathway analysis of the upregulated genes in the PVT1-overexpressing hepatocellular carcinoma cells revealed that the main pathway associated with PVT1 overexpression was the cell cycle pathway." (PMID 32117705, 2020). "Mechanism studies showed that PVT1 served as an endogenous sponge for miR-186-5p to reduce its inhibiting effect on yes-associated protein 1 and thus promoted the tumorigenesis of hepatocellular carcinoma." (PMID 30083911, 2019). "Ketamine can induce ferroptosis in hepatocellular carcinoma cells in vitro and in vivo, by reducing the expression of long non-coding RNA PVT1 (lnc PVT1) and GPX4, thereby triggering ferroptosis in hepatocellular carcinoma cells." (PMID 40959280, 2025). "The role of PVT1 in the pathogenesis of digestive system tumors, including promoting proliferation, metastasis, and autophagy of hepatoma cells, is well-established." (PMID 38745179, 2024). "PVT1, a major oncogenic long non-coding RNA in the gastrointestinal tract, is known to regulate the progression and drug resistance of hepatocellular carcinoma." (PMID 38745179, 2024). "Utilizing data from the TCGA database, we developed ceRNETs specific to hepatocellular carcinoma, revealing PVT1 as a potential ceRNA for PLAG1 through identification of central network nodes." (PMID 38745179, 2024). "PLAG1, regulated by the lncRNA PVT1, confers resistance to sorafenib-induced ferroptosis in hepatocellular carcinoma by upregulating GPX4 and maintaining redox homeostasis." (PMID 39315094, 2024). "PVT1 was also reported to be over-expressed in hepatocellular carcinoma, playing a key role in cancer cell proliferation, metastasis, and cell cycling." (PMID 36624401, 2023). "In contrast, Gdf15 is a downstream target of Pvt1 and was positively regulated by the lncRNA in hepatocellular carcinoma cells." (PMID 34364390, 2021). "One protein member of this pathway, MDM2 Proto Oncogene (MDM2), was stabilized by PVT1 via its interaction with Enhancer Of Zeste 2 Polycomb Repressive Complex 2 Subunit (EZH2) in the setting of hepatocellular carcinoma." (PMID 31710657, 2019). "Previous studies have shown that PVT1 can promote the proliferation of various types of cancer cells, such as hepatocellular carcinoma cells, thyroid cancer cells and so on." (PMID 29760583, 2018). "Tian reported that PVT1 promotes the tumorigenesis and metastasis of hepatocellular carcinoma by acting as a competing endogenous RNA for miR‐186‐5p 34, which is consistent with our analyses results." (PMID 29047230, 2017). "A recent study has found that PVT1 increases NOP2 levels by enhancing the stability of the NOP2 protein in hepatocellular carcinoma and that the function of PVT1 in cell proliferation is dependent on the presence of NOP2." (PMID 26545364, 2015). "Upregulation of PVT1 in hepatocellular carcinoma activates cell proliferation through stabilizing NOP2." (PMID 26517688, 2015).
hepatocellular carcinoma (continued). "The plasmacytoma variant translocation 1 (PVT1) is located at cancer risk region 8q24.21, which has been identified to aberrantly expressed in various cancers including pancreatic, prostate, bladder cancers, and hepatocellular carcinoma." (PMID 35036445, 2022). "In hepatocellular carcinoma, PVT1 promoted cell proliferation by recruiting Ezh2." (PMID 34335862, 2021). "For instance, HULC, up-regulated by CREB, could contribute to the initiation and progression of liver cancer through interacting with miR-372; lncRNA PVT1 favors hepatocellular carcinoma cell proliferation and stem cell-like property by stabilizing NOP2." (PMID 30987669, 2019). "A recent screening for liver oncofetal (i.e., fetal specific molecules misexpressed in cancer) lncRNAs in a mouse model for hepatocellular carcinoma (HCC) supported the role for PVT1 in regulating proliferation and the same phenotype was confirmed in human HCC cell lines." (PMID 25883951, 2015). "NOP2 is upregulated by microRNA PVT1 to promote hepatocellular carcinoma (HCC) proliferation and prostate cancer metastasis." (PMID 35562754, 2022). "The expression of lncRNA PVT1 in the hepatocellular carcinoma (HCC) tissues is increased when compared with that in the HBV-negative tissues." (PMID 34510316, 2022). "Furthermore, PVT1 participated in tumor progression of hepatocellular carcinoma patients." (PMID 27813492, 2016). "However, the association between PVT1 and hepatocellular carcinoma (HCC) remains unclear." (PMID 25624916, 2015). "In the latest of these reports, the authors found that a regulatory axis involving lncRNA PVT1, miR-378c, and DUSP13 is involved in microvascular invasion in hepatocellular carcinoma." (PMID 39062022, 2024). "In the present study, we explored the role of circRNA PVT1 in hepatocellular carcinoma (HCC)." (PMID 31551242, 2019). "We aimed to figure out the molecular network of PVT1 and EZH2 on hepatocellular carcinoma (HCC) cells growth." (PMID 30008615, 2018). "In hepatocellular carcinoma (HCC), hepatic oncofetal lncRNA PVT1 was up-regulated, and patients with high PVT1 expression had a poor clinical prognosis." (PMID 29108264, 2017). "PVT1 was reported to bind EZH2 and improve the EZH2 protein stability in hepatocellular carcinoma." (PMID 33763107, 2020). "Additionally, PVT1 inhibits miR-214 expression by interacting with EZH2 in ovarian cancer and hepatocellular carcinoma." (PMID 31497532, 2019). "In addition, PVT1 was shown to bind EZH2 and improve its stability in hepatocellular carcinoma." (PMID 33763107, 2020).